Y_RNA (Y RNA )
Gene: Miscellaneous RNA gene on chromosome 8 (42,949,388 to 42,949,495, reverse strand). Ensembl gene ENSG00000202514.
Homologues: Orthologues: chimpanzee Y_RNA (99% identical), macaque Y_RNA (94% identical), pig Y_RNA (74% identical). Paralogues in human: RNY1P5 (81% identical), Y_RNA (81% identical), Y_RNA (80% identical), Y_RNA (79% identical), Y_RNA (78% identical), Y_RNA (77% identical), RNY1P1 (76% identical), RNY1P6 (76% identical), Y_RNA (76% identical), RNY1 (75% identical), Y_RNA (75% identical), Y_RNA (74% identical), and 89 more.